PCSK9 (proprotein convertase subtilisin/kexin type 9)
Diseases named in the same sentence as PCSK9 in open-access papers (continued):
Sharing a sentence is not in itself a finding about the gene and the disease.
Hypercholesterolemia (continued). "Anti-PCSK9 monoclonal antibodies, also called the biological treatment for hypercholesterolemia or, simply, PCSK9-inhibitors (PCSK9-i), introduced the possibility of decreasing LDL-C levels by 40–60% when used additively to the maximum tolerated dose of lipid-lowering drugs." (PMID 31230174, 2019). "Although statins are currently the main treatment for hypercholesterolemia, many patients are statin intolerant and inhibition of proprotein convertase subtilisin/kexin type 9 (PCSK9) has recently emerged as an alternative or parallel approach to reduce cholesterol levels." (PMID 30646909, 2019). "Therefore, inhibition of PCSK9 function by monoclonal antibodies or gene expression by small molecules is a promising strategy for hypercholesterolemia therapy." (PMID 30704067, 2019). "Together, the results presented above, especially parallel expression of PCSK9 and HNF1α both in vivo and in vitro, suggest that up-regulation of HNF1α contributes to the increase in liver PCSK9 gene expression and leads to hypercholesterolemia in lipectomized rats." (PMID 30483910, 2019). "Monoclonal antibodies against PCSK9 which were developed for the treatment of familial hypercholesterolemia have been shown to decrease free PCSK9 levels in the plasma almost immediately along with a significant drop in plasma LDL-cholesterol levels as early as 1 day after administration." (PMID 31332258, 2019). "PCSK9 inhibitors may reduce the need for LA in patients with heterozygous or polygenetic hypercholesterolemia, but in some patients, a combination of these drugs with LA will be necessary." (PMID 29747383, 2018). "In addition, anti-PCSK9 drugs (evolocumab and alirocumab) provide an effective solution for patients with familial hypercholesterolemia (FH) and statin intolerance at very high cardiovascular risk." (PMID 29361723, 2018). "Patients in our adult lipid clinic (n = 109) receiving PCSK9 inhibition for atherosclerotic cardiovascular disease or familial hypercholesterolemia who had available pre- and post-PCSK9 inhibition standard nonfasting lipid data were, retrospectively, selected for data analysis." (PMID 30105099, 2018).
Hypercholesterolemia (continued). "For predicting hypercholesterolemia, the values of AUC remained the highest by sdLDL-C (0.726, 95% CI 0.672-0.779, p < 0.001), followed by apoC3 0.674, 95% CI 0.621-0.728, p < 0.001) and PCSK9 (0.609, 95% CI 0.564-0.654, p < 0.001)." (PMID 27713142, 2017). "PCSK9 RNA interference by Inclisiran may provide long term and effective management of hypercholesterolemia with administration every 3 or 6 months, as compared with the once or twice monthly regimen for the currently approved anti-PCSK9 antibodies." (PMID 29644225, 2017). "Moreover, when mice continued on western HFD for 5 weeks after injection of PCSK9 virus, the hypercholesterolemia triggered formation of atherosclerotic lesions within intimal hyperplasia (n = 3, data not shown)." (PMID 28716818, 2017). "In conclusion, maternal hypercholesterolemia might decrease the transportation of cholesterol from mother to fetus because of the high levels of PCSK9 protein expression." (PMID 28199412, 2017). "Identifying the FMRP regulated mRNAs or proteins as causal factors for hypocholesterolemia could have implications not only for identifying potential FXS biomarkers but also in finding novel PCSK9 inhibitors for the treatment of hypercholesterolemia." (PMID 28334053, 2017). "Therefore, this first meta-analysis was carried out to clarify the therapeutic efficacy and safety of PCSK9-mAbs on the potential patients: familial hypercholesterolemia and statin-intolerant patients." (PMID 28331223, 2017). "Coordinated up-regulation of Srebf-2 and Pcsk9 genes expression suggests that SREBP-2 may play a crucial role in regulation of Pcsk9 gene expression and consequently contribute to hypercholesterolemia observed in subjects with CKD." (PMID 26481479, 2016). "We tested a hypothesis that increased liver PCSK9 biosynthesis could be partially responsible for the elevated circulating PCSK9 level, and subsequently contribute to hypercholesterolemia observed in subjects with CKD." (PMID 26481479, 2016). "The coordinated up-regulation of Pcsk9 and Srebf-2 genes expression suggests that SREBF-2 may play a key role in regulation of Pcsk9 gene expression, circulating PCSK9 level, and hypercholesterolemia in experimental CRF." (PMID 26481479, 2016). "These include IHH involved in skeletal malformations, ROBO3 involved in horizontal gaze palsy with progressive scoliosis, PCSK9 involved in familial hypercholesterolemia, FAM83H related to amelogenesis imperfecta type 3 and GJA3 associated with congenital cataracts." (PMID 26861414, 2016). "Impelled by promising pre-clinical evidence, the clinical development of therapeutic inhibitors of PCSK9 has progressed rapidly, with promising results reported from phase 2 and 3 clinical studies, in statin-intolerant and familial hypercholesterolemia patients, with sub-optimal LDL-C levels." (PMID 27095708, 2016). "The first suggestion of a link between PCSK9 and hypercholesterolemia was published in 2003; a decade later, two meta-analyses of clinical trials comparing anti-PCSK9 treatment to placebo or ezetimibe, including >10,000 hypercholesterolemic individuals, were published." (PMID 26456772, 2015).
Hypercholesterolemia (continued). "Taken together, the published evidence from the phase 2 trials suggests that PCSK9 inhibition with monoclonal antibodies is an effective and well tolerated treatment option for a diverse patient populationswith hypercholesterolemia over a 12-week treatment period." (PMID 25470376, 2014). "In conclusion, the present mAbs results are very encouraging and may well lead to a novel approach to combat hypercholesterolemia and possibly other PCSK9-related pathologies." (PMID 23951290, 2013). "Indeed, the results of recent clinical trials show that antibody-mediated inhibition of PCSK9 can reduce the levels of low-density lipoproteins in patients with hypercholesterolemia by as much as 65–70%." (PMID 23580362, 2013). "Since the worldwide discovery of individuals harboring natural mutations of PCSK9, clinical studies have established a causative association between “gain of function” (GOF) mutations with hypercholesterolemia and “loss of function” (LOF) mutations with hypocholesterolemia." (PMID 23951290, 2013). "Since the validation by genetic studies that PCSK9 has a clear role in the regulation of cholesterol homeostasis, many efforts have been made to develop an inhibitor of this attractive therapeutic target for the treatment of hypercholesterolemia." (PMID 23951290, 2013). "The primary therapeutic indications for these drugs include hypercholesterolemia, coronary artery disease, myocardial infarction, and hyperlipidaemia—conditions collectively classified under cardiovascular diseases—all of which target and inhibit PCSK9 activity." (PMID 41283645, 2025). "However, the necessity for genotype identification and differentiation in FH and polygenic hypercholesterolemia therapy with PCSK9 inhibitors remains unclear." (PMID 37610687, 2025). "Proprotein convertase subtilisin/kexin type 9 (PCSK9) antibodies and small interfering RNA (siRNA) are major breakthroughs in cardiovascular therapeutics that have demonstrated unparalleled efficacy in alleviating hypercholesterolemia and reducing cardiovascular risk." (PMID 40006605, 2025). "As Pcsk9 is a target relevant to hypercholesterolaemia treatment and Hpd silencing can rescue the lethal phenotype of hereditary tyrosinemia type 1 in mice, we separately targeted eight sgRNA sites in Hpd and seven sgRNA sites in Pcsk9 with different deaminase CBEs." (PMID 38831042, 2025). "PCSK9 loss-of-function mutation carriers exhibit reduced LDL-C levels and are protected against atherosclerotic cardiovascular diseases (ASCVD), whereas PCSK9 gain-of-function mutation carriers present with familial hypercholesterolemia and are at high risk for ASCVD." (PMID 40338666, 2025). "Therefore, the purpose of this review is to discuss whether a patient’s genotype affects PCSK9 inhibitor efficacy in the treatment of familial hypercholesterolemia and how this might influence clinical management." (PMID 37610687, 2025). "​Furthermore, the Phe-MR analysis demonstrate that genetically predicted elevated PCSK9 levels were associated with an increased risk of cardiovascular diseases such as CHD and MI, as well as lipid metabolism disorders, including hyperlipidemia and hypercholesterolemia." (PMID 38689297, 2024).
Hypercholesterolemia (continued). "Further, gene variants, including apolipoprotein E (APOE) isoforms, and single-nucleotide polymorphisms in genes encoding the LDL-receptor (LDL-R), apolipoprotein B (apoB), and proprotein convertase subtilisin/kexin type 9 (PCSK9) may result in severe hypercholesterolemia and hypertriglyceridemia." (PMID 39796476, 2024). "Therefore, PCSK9 represents a therapeutic target for managing hypercholesterolemia." (PMID 38796450, 2024). "Notably, in a patient with drug-resistant hypercholesterolemia, serum PCSK9 concentrations surged by 15-fold, coinciding with the detection of HNF4-α overexpression, indicating that HNF4-α might also play a role in PCSK9 regulation." (PMID 39139638, 2024). "Thus, chromatin remodeling may help negate the adverse effects of statin treatment, primarily of increasing PCSK9 during hypercholesterolemia." (PMID 39566851, 2024). "Thus, PCSK9 antibodies (alirocumab and evolocumab) as well as small interfering mRNAs that inhibit intracellular synthesis of PCSK9 (inclisiran) are FDA approved drugs for adults with hypercholesterolemia and established or high risk of CVD." (PMID 38247511, 2024). "Familial hypercholesterolemia (FH) is a disorder characterized genetically by elevated blood low-density lipoprotein (LDL) cholesterol (LDL-C) levels, a risk factor for CVD, and the proprotein convertase subtilisin kexin 9 (PCSK9) is one of the key molecules in the pathophysiology of FH." (PMID 39519519, 2024). "PCSK9 mAbs, Evolocumab, Alirocumab, and Inclisiran, were approved for clinical usage shortly after their discovery and have since been extensively utilized not only for treating familial hypercholesterolemia (FH) but also for secondary prevention of atherosclerotic cardiovascular disease (ASCVD)." (PMID 38397888, 2024). "Therefore, targeted gene sequencing analysis was performed using custom panels focusing on the exome regions of 21 lipid-associated genes, including ABCG5, ABCG8, and familial hypercholesterolemia-causing genes (LDL receptor, LDLRAP1, PCSK9, and apolipoprotein B)." (PMID 38338819, 2024). "In addition, and unrelated to the ZHX-ANGPTL4 pathway, another recent study has shown that hypercholesterolemia of nephrotic syndrome is initiated by the secretion of PCSK9 from cortical collecting duct cells, where PCSK9 is a chaperone protein for the epithelial sodium channel (ENaC)." (PMID 37795536, 2023). "The elevation of plasma PCSK9 in this study may also contribute to hypercholesterolemia." (PMID 37892538, 2023). "Similar to cholesterol, triglycerides, and platelet activation, higher PCSK9 expression levels were observed, suggesting that a high-fat diet may increase PCSK9 levels and that both PCSK9 and hypercholesterolemia/hypertriglyceridemia synergistically modulate platelet hyperactivity." (PMID 37892538, 2023). "Hence, it is highly likely that PCSK9 inhibitors may inhibit both atherogenesis and atherothrombosis in hypercholesterolemia conditions, by disrupting CD36, LOX-1, and SARA expression." (PMID 35207479, 2022). "Furthermore, for lipid-lowering therapy, a particular siRNAs is revolutionizing the therapeutical approach to hypercholesterolemia: inclisiran, which achieves significant reduction in PCSK9 expression and subsequently in LDL levels with just two doses per year." (PMID 35807171, 2022). "Considering that the application of these antibodies is an already established therapy used to treat severe hypercholesterolemia with little adverse effects, peripheral PCSK9 inhibition could be a valuable tool to target cerebral Aβ accumulation in AD patients." (PMID 35344086, 2022).
Hypercholesterolemia (continued). "Overall, since the pharmacologicalefficacy of inclisiran in LDL-C reduction is comparable to that of monoclonalantibodies against PCSK9, the longer effect duration and the favorable safetyprofile may favor this newer approach for hypercholesterolemia management." (PMID 39076203, 2022). "Importantly, to the best of our knowledge, only a few previous studies have examined whether PCSK9 inhibitors induce any changes in hemostasis in patients with hypercholesterolemia." (PMID 35566668, 2022). "Thus, Nar-induced PCSK9 reduction may represent a prospective approach to effectively reduce hypercholesterolemia, avoiding the side effects often complained by statin users and the high costs of monoclonal antibodies." (PMID 36555447, 2022). "Hence, inhibition of PCSK9 has become a very potent tool for the treatment of hypercholesterolemia." (PMID 35162992, 2022). "Polyphenol-rich black currant reduced hypercholesterolemia, hyperglycemia, and liver steatosis, and also prevented diet-induced metabolic disturbances through the modulation of proprotein convertase subtilisin/kexin type 9 (PCSK9)/low-density lipoprotein receptor (LDL-R) pathways." (PMID 35630763, 2022). "The ODYSSEY OUTCOMES trial recently observed that alirocumab, a proprotein convertase subtilisin/kexin type 9 inhibitor used in the treatment of hypercholesterolaemia, could reduce both future type 1 and type 2 myocardial infarction by 13% and 22%, respectively, as compared to placebo." (PMID 34431993, 2022). "The inhibition of proprotein convertase subtilisin/kexin type 9 (PCSK9) via monoclonal antibodies (mAb), is a recent approach offering an additional treatment option for high-or very high-risk patients with hypercholesterolemia not reaching the LDL-C targets despite oral treatment." (PMID 35911507, 2022). "Thus, PCSK9 monoclonal antibody or siRNA therapy that is currently used in clinics worldwide to treat hypercholesterolemia could be useful to study as a combined therapeutic strategy for cancer/metastasis." (PMID 35806470, 2022). "These individuals have lower levels of low-density lipoprotein (LDL) cholesterol in the blood and a reduced risk of atherosclerotic cardiovascular disease, suggesting that disrupting the PCSK9 gene could be a promising strategy for the treatment of familial hypercholesterolemia." (PMID 35021064, 2022). "However, in line with our results, other drug utilization studies have reported that fewer than 1% of patients with ASCVD and/or heterozygous familial hypercholesterolemia added ezetimibe to statin therapy, and fewer than 1% of patients were prescribed PCSK9 inhibitors." (PMID 36054205, 2022). "Among additional repurposing drug candidates that could improve anti-tumor immune response, it was reported that, in analogy to PCSK9 deletion, PCSK9-neutralizing antibodies, clinically approved for hypercholesterolemia treatment, synergize with anti-PD1 therapy in different mouse cancer models." (PMID 34439102, 2021).